RNU6-1187P (RNA, U6 small nuclear 1187, pseudogene)
Gene: Small nuclear RNA gene on chromosome 4 (77,150,328 to 77,150,437, reverse strand). Ensembl gene ENSG00000201641.
Homologues: Orthologues: chimpanzee U6 (87% identical), macaque U6 (83% identical), dog U6 (78% identical), guinea pig U6 (73% identical), rabbit U6 (70% identical). Paralogues in human: RNU6-19P (82% identical), RNU6-364P (82% identical), RNU6-12P (81% identical), RNU6-13P (81% identical), RNU6-145P (81% identical), RNU6-26P (81% identical), RNU6-27P (81% identical), RNU6-31P (81% identical), RNU6-32P (81% identical), RNU6-49P (81% identical), RNU6-517P (81% identical), RNU6-536P (81% identical), and 1287 more.